BRAF (B-Raf proto-oncogene, serine/threonine kinase)
Diseases named in the same sentence as BRAF in open-access papers (continued):
Sharing a sentence is not in itself a finding about the gene and the disease.
melanoma (continued). "The RT-qPCR analysis demonstrated a significantly higher LOXL3 fold change gene expression in the BRAF+ melanoma than in the BRAF− melanoma (p = 0.0214), dysplastic nevus (p = 0.0035), and melanoma in situ (p = 0.0024)." (PMID 39273022, 2024). "The combination of the BRAF inhibitor and MEK inhibitor showed outstanding response rates in BRAF-mutated melanoma and is now considered the standard of care in this setting." (PMID 39776585, 2024). "The data suggest that brain metastases in BRAF-mutant melanoma are less responsive to BRAF inhibition." (PMID 39582535, 2024). "Platelet-derived growth factor receptor-beta (PDGFRβ), a critical factor in resistance, is enriched in EVs released by melanoma cells that are resistant to the BRAF inhibitor PLX4720." (PMID 39403600, 2024). "Previous and more recent findings by our lab implicated changes in ion channel expression and Ca2+ signaling as a mechanism of adaptation and drug tolerance to BRAFi in BRAF-mutant melanoma." (PMID 39001489, 2024). "We observed features of cellular senescence in NCSLC cells following EGFR inhibition and melanoma cells following BRAF inhibition." (PMID 38473364, 2024). "Previous literature has described glomerulonephritis associated with immune checkpoint inhibitors (ICIs) as well as BRAF/MEK inhibitors used to treat melanoma, all of which the patient had received in the past." (PMID 39677216, 2024). "Melanoma is one of the most aggressive cancers and treatment methods commonly used for patients with skin cancer include checkpoint and BRAF/MEK inhibitors, traditional chemotherapy drugs, radiation, and adjuvant treatment methods." (PMID 39473730, 2024). "The proliferative activity of human melanomas with BRAF V600E mutations increases with NRAS isoform 2 overexpression and concomitant resistance to BRAF inhibitor therapy." (PMID 38462618, 2024). "Among these mutations, BRAF and NRAS are two of the most common, but also mutually exclusive mutated oncogenes recognised in melanoma." (PMID 39766280, 2024). "Maldonado and coworkers reported that 9 patients out of 19 with BRAF mutations had an increased 7q number; on the other hand, 15 patients out of 49 with WT-BRAF melanomas exhibited an increased 7q number." (PMID 39727691, 2024). "Our work identifies multiple therapeutic strategies that delay melanoma recurrence after BRAF and/or MAPK inhibitor therapy." (PMID 38965534, 2024). "In line with this suggestion, it has been demonstrated that targeting CD20+ melanoma cells with rituximab significantly potentiates the BRAF inhibitor (vemurafenib)-mediated cell killing." (PMID 39199632, 2024). "For instance, Raf inhibitors such as vemurafenib are effective in the treatment of BRAF mutant melanoma; however, BRAF mutant colorectal cancer is resistant to vemurafenib due to feedback up-regulation of ERK signaling." (PMID 38277448, 2024). "Initially characterized in melanomas, various groups including ours have identified activating BRAF alterations across multiple cancers." (PMID 39018217, 2024). "We have succeeded in determining the most common mutations in the BRAF, NRAS, and TERT genes that cause melanoma." (PMID 39195270, 2024). "All the canine and equine melanoma cell lines retained their wild-type status of BRAF exon 15 and 11, NRAS exon 3, and KIT exon 11 according to WES." (PMID 38397192, 2024). "Similar to other mucosal melanomas, c-KIT, BRAF, and NRAS mutations are frequently detected in female genital melanomas." (PMID 38988710, 2024). "Altogether these findings suggest that miR-579-3p/MITF interplay potentially governs the balance between proliferation, senescence and resistance to therapies in BRAF-mutant melanomas." (PMID 38472212, 2024).
melanoma (continued). "After the development of resistance to BRAF/MEK inhibitors, these resistant melanoma cell lines are susceptible to pyroptosis, which can be induced by etoposide or doxorubicin, and the combination of temozolomide and chloroquine." (PMID 38336727, 2024). "The most frequent BRAF altered cancer types were melanoma (n = 1591), CRC (n = 1061), and NSCLC (n = 714)." (PMID 38275886, 2024). "The results of such analyses can facilitate the development of targeted treatments for BRAF-mutant melanomas." (PMID 39336897, 2024). "IGFBP3-mediated IGF1R activation was first observed in erlotinib-treated PC9 cells, and a similar mechanism was also described in BRAF (V600E) melanoma cells adapting to targeted BRAF inhibition." (PMID 38473364, 2024). "In particular, melanoma cells with neural crest stem cell state were enriched after treatment with BRAF/MEK inhibitors, and this cell state transition was mediated by retinoid X receptor signalling." (PMID 38241976, 2024). "The overall response rate (ORR) of the BRAF inhibitor plus MEK inhibitor (BRAFi/MEKi) combination therapy for BRAFV600-mutant advanced melanoma surpasses that of immune checkpoint inhibitors (ICIs)." (PMID 39337055, 2024). "The significance of BRAF dimerization in driving resistance was confirmed in a study using patient-derived xenograft models (PDX) established from metastasized human melanoma tumors." (PMID 38672652, 2024). "BRAF mutant tumors had the lowest median TMB (12.4 mutations/Mb), followed by NRAS mutant tumors (median 17.5 mutations/Mb) and TWT melanomas (28.2 mutations/Mb)." (PMID 38611025, 2024). "Therapeutic agents targeting oncogenic drivers, such as BRAF inhibitors in melanoma and CDK4/6 inhibitors in breast cancer, are currently established as the mainstays of cancer therapy." (PMID 38622197, 2024). "With the onset of targeted therapies, clinical trials such as coBRIM or COLUMBUS revealed the efficacy of specialized BRAF inhibitors in cases of BRAF exon 15 p.V600-mutant melanomas." (PMID 38539548, 2024). "Our study describes three melanoma patients who developed sarcoidosis while undergoing immunotherapy or BRAF-targeted treatment." (PMID 39717410, 2024). "We examined 20 BRAF-mutant melanomas treated with immunotherapy or targeted therapy and measured chromosomal aneuploidy and cGAS expression levels." (PMID 38473384, 2024). "Here, BRAF-mutant melanoma WM989 cells labeled with Rewind/FateMap expressed lineage barcodes were treated with vemurafenib, trametinib, a vemurafenib and trametinib combination, and an appropriate vehicle control." (PMID 38670101, 2024). "Polyamine biosynthesis signature is associated with poor prognosis and shorter progression free survival after BRAF/MAPK inhibitor treatment in melanoma cohorts, highlighting the clinical relevance of our findings." (PMID 38965534, 2024). "For comparison, we also studied the WM3918 human melanoma cell line that expresses wild-type BRAF, c-KIT, RAS, and CDK4 genes." (PMID 38254853, 2024). "The potential for these agents to be combined with established targeted therapies and immunotherapies warrants further investigation to determine their applicability in BRAF-mutant melanoma." (PMID 39336897, 2024). "The introduction of these drugs has completely revolutionized the medical therapy of BRAF-mutant melanomas." (PMID 39727691, 2024). "Novel BRAF small-molecule inhibitors, including vemurafenib, dabrafenib, and encorafenib, have been developed as therapeutic approaches for treating melanoma in response to this insight." (PMID 39195270, 2024).
melanoma (continued). "The optimal first-line regimen for BRAF-mutant melanomas remains contested, although it should consist of immunotherapy for most patients." (PMID 39001417, 2024). "EV20/MMAF had the ability to target melanoma cells and breast cancer cells specifically and efficiently, and the cell killing activity of ADCs was unaffected by the cells’ BRAF status." (PMID 38835349, 2024). "Melanoma patients over 65 treated with BRAF/MEK or c-KIT inhibitors were retrospectively identified, and their data were analyzed for treatment efficacy and toxicity." (PMID 39207855, 2024). "Further analyzes revealed overexpression of heme oxygenase 1 and the activation of the AKT pathway in association with nuclear BRAF V600E and cell proliferation in BRAF inhibitor resistant melanoma cells." (PMID 39272837, 2024). "The progression of a BRAF-mutant mouse melanoma was suppressed in vivo upon YAP1 ablation in cancer-associated fibroblasts (CAFs)." (PMID 38308096, 2024). "High-grade CNM+ melanomas (G3-CNM+) were more frequently ulcerated (p = 0.025), and BRAF (V600E) mutated (p = 0.028)." (PMID 39099686, 2024). "In melanomas, the hyperactivation of the MAPK pathway is mainly through activating mutations in BRAF, NRAS, NF1, and KIT." (PMID 38247727, 2024). "Trametinib (GSK1120212) is an oral, reversible and selective allosteric inhibitor of MEK1/2 and is FDA-approved for the treatment of metastatic BRAFV600E mutant NSCLC and melanoma, in combination with BRAF inhibitors." (PMID 38643157, 2024). "This review explores the advancements and difficulties in personalized immunotherapy for BRAF-mutant melanoma." (PMID 39336897, 2024). "MAPK activation in melanoma cells that are resistant to BRAF inhibitors promotes the expression of PD-L1; however, MEKi combinations showed a downregulation of MAPK and a suppression of PD-L1 expression." (PMID 38339003, 2024). "Unfortunately, her melanoma progressed and she was switched to BRAF targeting treatment with encorafenib and binimetinib before her second nivolumab dose." (PMID 39157612, 2024). "B-RAF inhibitors vemurafenib and dabrafenib, and MEK1/2 inhibitor trametinib have improved the clinical outcomes of melanoma patients with BRAF V600E/K mutant." (PMID 39372954, 2024). "In particular, only 2 of these, both BRAF p.V600E, were only detected in the tumor: one in a melanoma patient (GE14) who had a brain metastasis and the other one in a sarcoma patient (GE1) undergoing metastasectomy for the lung metastases." (PMID 38750555, 2024). "For BMs of BRAF-mutant melanoma, BRAF inhibitors such as vemurafenib and dabrafenib are active in treating BMs." (PMID 39061222, 2024). "It is reported that ELP3 plays a key role in hypoxia-inducible factor-1α (HIF-1α) translation by a codon-specific mechanism and promotes resistance to serine/threonine-protein kinase B-Raf (BRAF) inhibition in melanoma." (PMID 37771073, 2024). "Those treated with immunotherapy first had significantly better outcomes than those treated with targeted therapy, suggesting immunotherapy should be strongly considered as the first-line therapy for patients bearing BRAF-mutant melanoma." (PMID 38473384, 2024). "In view of the fact that the OFA includes some relevant genes in melanoma pathways apart from BRAF, such as NRAS, KIT, or MAP2K1, we embraced this panel to prospectively study a series of advanced melanoma patients." (PMID 39000050, 2024). "Our findings strongly suggest that modifications of tumor metabolism are essential mechanisms responsible for the efficacy of BRAF inhibitors as therapeutic agents in melanoma." (PMID 38254853, 2024). "Taken together, the addition of at least 125 nM CuET to trametinib resulted in a complete inhibition of cell viability in BRAF WT melanoma cells after three days." (PMID 38263136, 2024).
melanoma (continued). "In vivo, 1H and 31P magnetic resonance spectroscopy were used to study human melanoma models to monitor the metabolic effects of dabrafenib therapy, an inhibitor of the hyperactive BRAF protein in melanoma." (PMID 38254853, 2024). "The combinations of BRAF inhibitor-based targeted therapies with immune checkpoint inhibitors currently represent less common therapeutic approaches in advanced melanoma." (PMID 39684531, 2024). "Many dysregulated genes were observed in the BRAF(V600E) mutant group compared to the wild-type BRAF group for colon cancer, thyroid cancer, and melanoma, respectively." (PMID 39052013, 2024). "In this study, we have identified metabolic biomarkers that predict early and reliably the response or the resistance to BRAF inhibition in preclinical human melanoma models." (PMID 38254853, 2024). "In this single-center retrospective study, we analyzed the prognostic performance of clinicopathological features and routinely available blood biomarkers in patients with BRAF V600 mutant unresectable advanced melanoma treated with BRAF + MEK inhibitor." (PMID 39272837, 2024). "In the present study, we investigated the effects and possible mechanisms of action of alantolactone on BRAF-mutant melanoma with the aim of providing basic research for potential treatment options for melanoma." (PMID 38822350, 2024). "Trametinib, an FDA approved mitogen-activated protein kinase kinase (MEK) inhibitor, is used to treat melanoma patients with BRAF V600E." (PMID 38356704, 2024). "In approximately 4–25% of patients, melanoma has been correlated with the inter-tumor heterogeneity of BRAF." (PMID 39336897, 2024). "Dabrafenib therapy in BRAF-mut melanoma increases T-cell infiltration and sensitizes the tumors to immune checkpoint inhibition therapy." (PMID 38421883, 2024). "Of note, experimental data suggest that BRAF inhibitor treatment can reduce IDO1 expression, while high IDO1 levels can be detected in melanoma samples in connection with the development of resistance to the BRAF inhibitor." (PMID 39272837, 2024). "BRAF/MEK inhibitors like vemurafenib, dabrafenib and trametinib are often used in the treatment of melanoma with BRAF V600 mutations, but those therapies also have their limitations." (PMID 39598629, 2024). "We previously reported that miR-579-3p is a negative regulator of the BRAF-MAPK signaling pathway in melanoma because it targets BRAF kinase." (PMID 38472212, 2024). "The treatment landscape for BRAF-mutant melanoma is rapidly evolving, particularly with the development of next-generation BRAF inhibitors aimed at overcoming resistance mechanisms inherent to current therapies." (PMID 39336897, 2024). "The addition of the OXPHOS inhibitors enhanced the cytotoxicity against melanoma only when combined with the BRAF inhibitor vemurafenib." (PMID 39501277, 2024). "While the IC50 values of vemurafenib in the BRAFV600E mutant melanoma cells were less than 0.5 μM, the BRAF WT melanoma cells had an IC50 of more than 20 μM." (PMID 39063187, 2024). "Combinatorial alterations driving tumor evolution will likely vary across BRAF-mutant cell lines given the diversity in gene and protein expression that has been documented in melanoma cell lines." (PMID 38213996, 2024). "Approximately 90% of melanoma patients experience a complete or partial response or disease stabilization as a result of treatment with BRAF and MEK inhibitors." (PMID 38601651, 2024). "In vivo, BRAF/MEK inhibitors act in concert with RIG-I ligands to synergistically improve the survival of melanoma-bearing mice." (PMID 39165562, 2024). "The recent identification of mutations resulting in constitutive activation of BRAF, a protein kinase that activates ERK, has led to the development of useful drugs that target late-stage melanoma." (PMID 38363129, 2024). "In BRAF-mutant surgically resected melanoma stage III patients, the safety and efficacy of BRAF inhibitors associated with an MEK inhibitor were explored." (PMID 39727691, 2024).
melanoma (continued). "Supporting this observation, p62-KO mice with overexpression of BRAF-V600E showed inhibition of melanoma development and metastasis." (PMID 38519031, 2024). "Later, BAY 87‐2243 was demonstrated to reduce the viability of melanoma cells and tumor growth from BRAF mutant melanoma xenografts." (PMID 38214418, 2024). "Within melanoma, Apical Junction, Wnt-beta Catenin Signaling, and UV Response pathways were significantly altered between either Class 2 or Class 3 BRAF mutant tumors." (PMID 38275886, 2024). "The constitutive high expression of αvβ3 in melanoma and its interplay with BRAF signalling render it an attractive starting point for investigating combination therapy." (PMID 39063187, 2024). "Unfortunately, after the first sensitive period, relapse, and resistance to these BRAF inhibitors are observed in most melanoma cases." (PMID 38778340, 2024). "A 48-year-old woman with Stage IIIb BRAF wild-type melanoma, receiving nivolumab every 4 weeks, developed systemic sarcoidosis after seven cycles, primarily affecting extrapulmonary sites." (PMID 39717410, 2024). "When we compared the NES mRNA fold change gene expression in all tissues examined, we detected a significantly higher expression score in BRAF+ melanoma than in dysplastic nevus (p = 0.0357) and melanoma in situ (p = 0.0367)." (PMID 39273022, 2024). "Our findings reveal a more synergistic but narrower dosing landscape in NRAS vs. BRAF mutant melanoma, which we link to a mechanism of adaptive resistance through negative feedback." (PMID 39199684, 2024). "Combination strategies including BRAF/MEK-targeted therapies with ICI therapies are effective first-line options for advanced, BRAF-mutant melanoma; however, they are associated with more frequent side effects." (PMID 39684531, 2024). "A compound disrupting the eIF4F complex attenuated the growth of BRAF inhibitor-resistant melanomas." (PMID 39436655, 2024). "To assess the contribution of YAP1 signaling in CAFs to BRAF-mutant melanoma progression in vivo, we generated a transgenic mouse model, α-SMA-CreERT2; Yap1loxP/loxP, which allows the inducible ablation of YAP1 expression in CAFs." (PMID 38308096, 2024). "By overlapping the elevated gene lists in BRAF(V600E) mutant colon cancer, thyroid cancer, and melanoma, 20 genes were screened out to be overexpressed in the BRAF(V600E) mutant group across all three tumor types." (PMID 39052013, 2024). "One study evaluated IACS‐010759 (OPi), a mitochondrial oxidative phosphorylation complex I inhibitor, against MAPKi‐resistant BRAF‐mutant melanomas, demonstrating significant antitumor activity in vitro and in vivo." (PMID 39494561, 2024). "Cobimetinib is another MEK inhibitor that is utilized in conjunction with BRAF inhibitors in some malignancies, including melanoma." (PMID 38501105, 2024). "Here, we take a systems-biology approach, using proteomics and genomics to examine the development of drug tolerance to EGFR inhibitors in EGFR-mutant lung adenocarcinoma cells and BRAF inhibitors in BRAF-mutant melanoma cells." (PMID 38473364, 2024). "Currently, there is a phase III trial for the use of a combination of the BRAF/MEK inhibitors encorafenib and binimetinib for the adjuvant treatment of BRAF V600-mutant stage IIB/IIC melanomas after complete resection." (PMID 39123418, 2024). "Specifically, NAMPT is the rate-limiting enzyme of the NAD+ salvage pathway in mammals and increases in its expression/activity play key roles in melanoma therapeutic resistance to BRAF/MEKi." (PMID 38755661, 2024). "In particular we show that miR-579-3p is specifically deregulated in BRAF-mutant melanomas and that its expression levels mirror those of MITF." (PMID 38472212, 2024). "As increased DUSP1 and DUSP5 expression occurred with corin treatment of BRAFi-R melanoma cells, we sought to establish baseline levels of DUSPs in BRAF-sensitive and BRAF-resistant melanoma cell lines." (PMID 38300709, 2024).